SEPTIN12 (septin 12)
Description:
Filament-forming cytoskeletal GTPase (By similarity). Involved in the morphogenesis of sperm heads and the elongation of sperm tails probably implicating the association with alpha- and beta-tubulins. Facilitates the formation of Septin filament structures with SEPTIN7, SEPTIN6, SEPTIN2 and SEPTIN4 at the sperm annulus. Correct formation of the annulus is required for development of normal structural morphology and motility of the sperm during steps 13 to 16 of spermiogenesis. Essential component of the LMNB1/SUN5/SEPT12 bridge that connects the sperm proximal centriole to the implantation fossa, the bridge functions to prevent detachment of the proximal centriole from the posterior nucleus during steps 13 to 16 of spermiogenesis. Required for PLCZ1 localization at the sperm acrosome during spermiogenesis (By similarity). May also play a role in the initiation of calcium oscillations in embryos (By similarity).
Synonyms: SEPT12; FLJ25410; SPGF10
Tractability: Small molecule: a structure with a bound ligand is known.
Gene: Protein-coding gene on chromosome 16 (4,777,606 to 4,788,398, reverse strand). Ensembl gene ENSG00000140623.
Subcellular location: Cytoplasm; Cytoplasm, cytoskeleton; Cytoplasm, cytoskeleton, spindle; Nucleus; Cell projection, cilium, flagellum; Cytoplasmic vesicle, secretory vesicle, acrosome
Subcellular location (Human Protein Atlas): Microtubules; Annulus
Gene Ontology:
Molecular function: GTP binding; identical protein binding; protein binding; protein homodimerization activity; GDP binding; GTPase activity; molecular adaptor activity; phosphatidylinositol binding
Biological process: septin ring assembly; spermatid development; cytoskeleton-dependent cytokinesis; flagellated sperm motility; intracellular protein localization; positive regulation of protein localization
Cellular component: microtubule cytoskeleton; midbody; nucleus; perinuclear region of cytoplasm; septin complex; sperm annulus; spindle; cell division site; cleavage furrow; septin ring; sperm head-tail coupling apparatus; stress fiber; acrosomal vesicle; cytoplasm; cytoskeleton; motile cilium
Genetic constraint (gnomAD): Loss-of-function variants: 39 observed, 32.57 expected, observed/expected ratio (o/e) 1.2, 90% interval 0.93 to 1.56. The synonymous counts are far from expectation, so gnomAD's model fits this gene poorly and the ratio says little. Missense variants: 597 observed, 468.57 expected, observed/expected ratio (o/e) 1.27, 90% interval 1.19 to 1.36. Synonymous variants: 246 observed, 192.58 expected, observed/expected ratio (o/e) 1.28, 90% interval 1.15 to 1.42.
Homologues: Orthologues: chimpanzee SEPTIN12 (99% identical), macaque SEPTIN12 (98% identical), pig SEPTIN12 (88% identical), guinea pig SEPTIN12 (87% identical), dog SEPTIN12 (86% identical), mouse Septin12 (85% identical), rat Septin12 (85% identical), rabbit SEPTIN12 (70% identical), zebrafish septin12 (60% identical), tropical clawed frog septin12 (58% identical). Paralogues in human: SEPTIN9 (57% identical), SEPTIN3 (53% identical), SEPTIN7 (40% identical), SEPTIN2 (39% identical), SEPTIN5 (39% identical), SEPTIN1 (37% identical), SEPTIN6 (34% identical), SEPTIN8 (34% identical), SEPTIN11 (34% identical), SEPTIN10 (33% identical), SEPTIN14 (32% identical), TMEM250 (7% identical).
Diseases named in the same sentence as SEPTIN12 in open-access papers:
SEPTIN12 is named in the same sentence as 10 diseases in open-access papers, as found by Europe PMC text mining. Sharing a sentence is not in itself a finding about the gene and the disease. The quoted sentences say what the papers report.
infertile (17 papers, 2012 to 2024). "We sequenced the ten exons of SEPTIN12 by Sanger sequencing and detected novel dominant mutations in exon (c.287T > C) in 2 infertile men." (PMID 39850804, 2024). "Numerous mutations of SEPTIN12 have been detected in infertile males, strongly indicating that SEPTIN12 is a pivotal gene linked to male infertility." (PMID 39850804, 2024). "Various mutations of SEPTIN12 have been identified in infertile males, implying SEPTIN12 as a male infertility gene." (PMID 35547809, 2022). "Consistently, in addition to the SEPTIN12 mutation, heterozygous mutations were identified in three other infertility genes in the male patient." (PMID 35547809, 2022). "We also observed a round head and a broken acrosome in the spermatozoa of infertile men with SEPTIN12 mutations and genetic variants (unpublished data)." (PMID 24213608, 2013). "Mutations and genetic variants of SEPTIN12 in infertility cases also caused oligozoospermia and teratozoospermia." (PMID 24213608, 2013). "Our previous studies have indicated that SEPTIN12+/+/+/− chimeras with a SEPTIN12 mutant allele were infertile." (PMID 24213608, 2013). "In humans, SEPTIN12 mutations and genetic variants were identified in infertile men presenting oligoasthenozoospermia with distinctive sperm pathology: a bent tail and a defective annulus." (PMID 24213608, 2013). "Previously, we screened 400 infertile men and 360 fertile men to assess whether the SEPTIN12 mutation was responsible for male infertility." (PMID 39850804, 2024). "Further studies are necessary to address whether compound mutations of SEPTIN12 and other infertility genes lead to infertility." (PMID 35547809, 2022). "The male infertility in Septin12−/− mice seems to be conflicted with the infertile phenotype in the male patient with a heterozygous c.72C>A SEPTIN12 mutation." (PMID 35547809, 2022). "In this study, we sequenced the entire coding region of SEPTIN12 in infertile men (n = 160) and fertile controls (n = 200) and identified ten variants." (PMID 22479503, 2012). "SEPTIN12, identified by c-DNA microarray analysis of infertile men, is exclusively expressed in the post meiotic male germ cells." (PMID 22479503, 2012). "A total of 160 infertile men with abnormal semen parameters and 200 fertile controls were subjected to SEPTIN12 sequence analysis." (PMID 22479503, 2012). "In summary, complete loss of Septin12, but not haploinsufficiency of Septin12, causes FF and infertility." (PMID 35547809, 2022). "Moreover, it has been reported that male Septin12+/− chimera mice are infertile, indicating that haploinsufficiency of Septin12 may lead to male infertility." (PMID 35547809, 2022). "Surprisingly, Septin12−/− male mice, but not Septin12+/− male mice, are infertile, and have reduced sperm counts and abnormal sperm morphology." (PMID 35547809, 2022). "In this study, we showed that Septin12−/− male mice, but not Septin12+/− male mice, are infertile." (PMID 35547809, 2022).
male infertility (9 papers, 2012 to 2025). The inability of the male to effect fertilization of an ovum after a specified period of unprotected intercourse. "SEPTIN12 is a crucial testis-specific gene essential for the final differentiation of male germ cells and is strongly linked to male infertility due to numerous detected mutations." (PMID 39850804, 2024). "In contrast, given that male Septin12+/− chimera mice are infertile, haploinsufficiency of Septin12 was believed to cause male infertility." (PMID 35547809, 2022). "Male Septin12+/− chimera mice were infertile, supporting the prevailing view that SEPTIN12 haploinsufficiency causes male infertility." (PMID 35547809, 2022). "Our findings indicated a genetic variant of SEPTIN12 is causally linked to male infertility with distinctive sperm pathology." (PMID 22479503, 2012). "Our findings provide the first clue about a causal link between SEPTIN12 genetic variant and male infertility with distinctive sperm pathology." (PMID 22479503, 2012). "In this study, a SEPTIN12 genetic variant (c.474G→A) was found to be significantly associated with male infertility with distinctive sperm pathology." (PMID 22479503, 2012). "This study provides the first causal link between SEPTIN12 genetic variant and male infertility with distinctive sperm pathology." (PMID 22479503, 2012). "Previous studies have reported that SEPTIN12 mutations, including c.266C > T/p; Thr89Met, c.616del; p.A206Pfs*10, c.589G > A/p; D197N, E282A, and c.474G > A cause male infertility." (PMID 39850804, 2024). "The SEPTIN12 gene has been associated with male infertility." (PMID 35547809, 2022). "Nevertheless, we cannot rule out the possibility that heterozygosity for the null SEPTIN12 mutation leads to male infertility in the human, but not in the mouse, due to species difference." (PMID 35547809, 2022). "Taken together, our data indicated that homozygous knockout of Septin12, but not Septin12 haploinsufficiency, leads to male infertility and FF." (PMID 35547809, 2022). "However, no pups were born through the mating between Septin12−/− male and WT female mice, indicating male infertility of Septin12−/− mice." (PMID 35547809, 2022).
teratozoospermia (9 papers, 2012 to 2024). "Previous studies showed a connection between point mutations of the GTP binding domain of Septin12 with teratozoospermia, asthenoteratozoospermia, and oligoasthenozoospermia." (PMID 39524225, 2024). "We presume that the loss of Septin12 decreases its polymerization ability, thus leading to teratozoospermia by disturbing sperm head formation." (PMID 30189608, 2018). "We discovered that mutated SEPTIN12 in different codons resulted in teratozoospermia or oligozoospermia." (PMID 30189608, 2018). "Several teratozoospermia-associated gene mutations, including F-box only protein 43 (FBXO43), armadillo repeat-containing protein 2 (ARMC2), SEPTIN12, and AGBL carboxypeptidase 5 (AGBL5), have been identified by measuring exonic mutations in blood samples using whole exome sequencing technology." (PMID 36292606, 2022).
asthenozoospermia (5 papers, 2015 to 2025). "Previous studies reported a decreased level of Septin 12 in men suffering from asthenozoospermia and correlated Septin 12 malfunction with sperm morphology abnormalities." (PMID 39524225, 2024). "In humans, patients with low sperm motility (asthenozoospermia) have imbalanced histone–protamine 1/2 ratio, modified levels of cytoskeletal proteins and we detected retained Septin 12 isoforms (Mw 40 and 41 kDa) in the sperm membrane, chromatin-bound and tubulin/mitochondria protein fractions." (PMID 39524225, 2024).
SEPTIN12 also shares sentences with these, for which no sentence is quoted: Azoospermia (2 papers); testicular embryonal carcinoma (2); Alzheimer disease (1); oligospermia (1); Sertoli Cell-Only Syndrome (1); testicular cancer (1).